HNF1B (HNF1 homeobox B)
Diseases named in the same sentence as HNF1B in open-access papers (continued):
Sharing a sentence is not in itself a finding about the gene and the disease.
diabetes (continued). "Eight (38%) individuals (GCK [four], WFS1 [two], HNF1B [one] and LMNA [one]) had been diagnosed with monogenic diabetes during their clinical follow-up, irrespective of our study." (PMID 36418577, 2023). "For instance, microdeletions of Chromosome 17q12 (which contains HNF1β gene), have been described to occur de novo in patients with CAKUT with or without diabetes mellitus." (PMID 28398236, 2017).
MODY (111 papers, 2009 to 2026). "HNF1B haploinsufficiency causes maturity onset diabetes of the young (MODY) including pancreas atrophy, while homozygous disruption of hnf1ba in zebrafish leads to a failure of pancreas development during embryogenesis." (PMID 41781333, 2026). "Mutations in HNF1A, PDX1, and HNF1B, which affect pancreatic development, have been associated with increased risk of monogenic forms of maturity onset diabetes of the young (MODY types 3, 4, and 5) and pancreatic cancer." (PMID 40427173, 2025). "Patients with hepatocyte nuclear factor-1 beta (HNF1B) mutations present a variable phenotype with two main symptoms: maturity onset diabetes of the young (MODY) and polycystic kidney disease (PKD)." (PMID 35179657, 2022). "For example, mutations in the transcription factor hepatocyte nuclear factor 1 homeobox B (HNF1B) gene have been shown to cause renal malformations, hypomagnesemia, and maturity-onset diabetes of the young (MODY)." (PMID 33200256, 2021). "The other susceptible gene causing maturity-onset diabetes of the young (MODY) is the transcription factor TCF2/HNF1B involved in β-cell development and function, and is reported to be negatively associated with overall survival in breast cancer (HR = 1.69, p = 0.0044)." (PMID 37510134, 2023). "In humans, heterozygous mutations of HNF1B are associated with several diseases such as pancreatic β-cell dysfunction leading to maturity-onset diabetes of the young (MODY5), defective kidney development, disturbed liver function, pancreas atrophy, and malformations of the genital tract." (PMID 22438943, 2012). "The discovery of HNF1β gene mutations as a cause of developmental kidney disease originally emerged from studies on MODY." (PMID 40313719, 2025). "We included HNF1B‐MODY because variants in HNF1B accounted for approximately 15% of all MODY cases in our Chinese cohort." (PMID 40966384, 2025). "Considering the clinical manifestations observed in the proband, gene panel sequencing identified a heterozygous HNF1B variant, c.36_38delCCT/p.(Leu13del) (reference transcript ID: NM_000458.4), as the most likely cause of MODY in the proband." (PMID 39337310, 2024). "As a result, gene panel sequencing identified a heterozygous HNF1B variant, c.36_38delCCT/p.(Leu13del), as the most probable cause of MODY in the proband (Reference transcript ID: NM_000458.4)." (PMID 39337310, 2024). "The patient’s clinical presentation was consistent with MODY caused by the HNF1B variant, showing signs of glucose intolerance, renal cysts, hepatic cysts, and agenesis of the dorsal pancreas." (PMID 39337310, 2024). "Over 200 HNF1B mutations have since been identified, with the kidney and pancreas being the most commonly affected organs, leading to MODY and renal abnormalities." (PMID 39337310, 2024). "The HNF1B MODY accounts for < 5% of all MODY subtypes, while mutations in KCNJ11 MODY are very rare and found in < 1% of all MODY cases." (PMID 39420905, 2024). "DM, the second most common feature of HNF1B defects, has been observed in 5–50% of HNF1B mutation carriers in previous studies, accounting for approximately 5% of cases of MODY." (PMID 39337310, 2024). "Large genomic rearrangements, such as full deletion of the HNF1B gene or full deletion of 17q12 locus, have been shown to cause HNF1B-MODY (MODY5) and can be missed by conventional point mutation screening." (PMID 38635808, 2024). "HNF1B-associated MODY accounts for approximately 6% of all MODY cases, characterized by declining insulin secretion leading to progressive hyperglycemia." (PMID 39337310, 2024). "HNF1B-related MODY has been also associated with a range of extrapancreatic manifestations not related to the genitourinary tract." (PMID 37511676, 2023). "The subtype 5 (HNF1B-MODY) is a rare form of the disease caused by HNF1B gene variants or whole gene deletions and it accounts for 2–5% of all MODY subtypes." (PMID 36793123, 2023).
MODY (continued). "In the case of HNF1B-related MODY caused by gene deletion, a portion of the HNF1B gene is missing, producing a shortened and ineffective version of the protein." (PMID 37511676, 2023). "In personalized medicine, the approach to a liver lesion in HNF1B-related MODY would be to understand the underlying genetic condition rather than investigate the cause of liver damage." (PMID 37511676, 2023). "HNF1B-related MODY caused by a gene mutation involves a change in the DNA sequence of the HNF1B gene that alters the structure or function of the protein." (PMID 37511676, 2023). "The most commonly found cases arise from mutations in GCK, HNF4A, HNF1A and HNF1B, accounting for up to 80% of all diagnosed MODY." (PMID 35008927, 2022). "For instance, multiplex ligation-dependent probe amplification led to the identification of two de novo mutations (deletions) in the HNF1B gene in suspected MODY cases in a Greek cohort." (PMID 36613572, 2022). "Mutations in the HNF1b gene are responsible for the development of HNF1b/MODY, which is associated with distinctive clinical features, including pancreatic atrophy and renal disease." (PMID 33259036, 2021). "Previously, we described an isolated case of HNF1B mutation in a Brazilian patient with familial DM and hypomagnesemia recruited due to suspicion of MODY." (PMID 31066763, 2019). "The HNF1B gene was associated with cystic kidney disease shortly after being first described as a cause of MODY by Horikawa and cols." (PMID 31066763, 2019). "Compared to other MODY genes, a high rate of de-novo mutations in HNF1β has been reported in the literature." (PMID 29764441, 2018). "Compared to GCK, HNF1A, HNF4A, and HNF1B, protein truncating mutations in the other MODY genes are less frequent causes of MODY." (PMID 29207974, 2017). "To assess these four methods, we processed DNA samples from two MODY patients with a known causal mutation in HNF1B, and then we compare sequencing coverage of targeted regions and variant detection." (PMID 26599467, 2015). "Nonetheless, it is noteworthy that all enrichment methods (including Nextera and Haloplex) did identify the mutation causing MODY in each patient (p.Gln382* in HNF1B for Patient #1 and p.His69_Lys71delinsArg in HNF1B for Patient #2)." (PMID 26599467, 2015). "Heterozygous mutations in the genes encoding the glycolytic enzyme glucokinase and the transcription factors, HNF-1α, HNF-4α and HNF1β have been shown to cause MODY." (PMID 24299156, 2014). "The HNF1B variant found in patient 4 has been reported as clinically significant in two previous studies, while the variant found in patient 5 was previously classified as pathogenic and associated with MODY." (PMID 39364395, 2024). "The clinical presentation of the patient was consistent with MODY caused by the HNF1B variant, including glucose intolerance, renal cysts, hepatic cysts, and agenesis of the dorsal pancreas, which is aligned with renal cysts and diabetes syndrome (OMIM #137920)." (PMID 39337310, 2024). "In addition, individuals with HNF1B-related MODY have an increased risk of developing metabolic disorders such as hyperlipidemia, including a low high-density lipoprotein level and elevated triglyceride level." (PMID 37511676, 2023). "Patients harboring heterozygous HNF1B mutations suffer from MODY, but may also feature pancreas exocrine dysfunction as well as kidney and liver abnormalities and vaginal and uterine malformation." (PMID 34079523, 2021). "Recently, several novel mutations in HNF1B and their relation to MODY were reported." (PMID 34299172, 2021). "Maturity-onset diabetes of the young (MODY), a monogenic form of diabetes, can result from mutations in one of the genes expressed in β-cell that include GCK, HNF1A, HNF1B, HNF4A, PDX1, and B2M." (PMID 33113859, 2020).
MODY (continued). "Both mutations cause maturity-onset diabetes of the young (MODY), and HNF1A forms heterodimers with HNF1B through their N-terminal dimerization interfaces." (PMID 28100260, 2017). "The HNF1B gene encodes a transcription factor and it was initially identified as a MODY gene." (PMID 20526366, 2010). "Furthermore, half of the patients with HNF1B-MODY have de novo mutations, and half of them also carry a large heterozygous deletion, which is in contrast with other types of MODY, where the mutations are mostly inherited from one of the parents and are usually a small-scale missense mutation." (PMID 34440499, 2021). "Patients with MODY (maturity onset diabetes of the young), which is caused by mutations in an autosomal dominant gene, are known to show distinct phenotypes between the HNF1B (MODY5) and HNF1A (MODY3) mutations due to differences in the expression level and the time and site of their expression." (PMID 27196561, 2016). "In India, targeted next-generation sequencing of 10 MODY genes in 56 patients identified potentially pathogenic variants in HNF4A, GCK, HNF1A, PDX1, HNF1B, NEUROD1, and PAX4 in 11 individuals, suggesting a more complex etiological spectrum in this population." (PMID 41153735, 2025). "Many MODY-associated TF genes show incomplete penetrance, e.g., HNF1A, HNF1B, HNF4A, NEUROD1, PDX1, and RFX6." (PMID 41356216, 2025). "Of these cases, 80% are contributed by variants in common genes associated with maturity‐onset diabetes of the young (MODY), including glucokinase (GCK), hepatic nuclear factor (HNF)‐1A, HNF1B and HNF4A." (PMID 40966384, 2025). "Two key studies from that country have significantly advanced the understanding of MODY genetics by identifying mutations primarily in GCK, HNF1A, and HNF1B genes." (PMID 41020216, 2025). "Mutations in seven of these genes, including ABCC8, GCK, HNF1B, INS, KCNJ11, NEUROD1, and PDX1, are implicated in both NDM and MODY." (PMID 39859454, 2025). "Almutair and Almulhem (2024) investigated the use of semaglutide, a GLP-1 receptor agonist, in patients with HNF1B-MODY." (PMID 40149950, 2025). "HNF1B-MODY is another type that is most frequently managed with insulin therapy but lacks a defined precision treatment." (PMID 38524636, 2024). "Considering these expression patterns and the age of onset for MODY, we believe that an impaired HNF-1A–mediated gene transcription is likely the disease-causing factor, even though an involvement of HNF-1B in disease predisposition or progression is possible." (PMID 38855865, 2024). "Dipeptidyl peptidase‐4 inhibitors (DPP‐4i) were used by 4.1% in individuals with HNF1B‐MODY and were less common in the other MODY types." (PMID 39511990, 2024). "The clinical presentation of HNF1B-MODY varied among patients, and it is often be misdiagnosed as either type 1 (T1DM) or type 2 diabetes mellitus (T2DM)." (PMID 39221224, 2024). "HNF1B MODY (previously MODY5) accounts for approximately 2–6% of all MODY cases and is the fourth most common type." (PMID 39408828, 2024). "Patients with HNF1B-MODY often respond poorly to oral hypoglycemic agents such as sulfonylureas, with early insulin therapy required in up to 80% of cases." (PMID 39337310, 2024). "Regarding management of patients with HNF1B MODY, sulfonylureas, GLP-1 analogs, and meglitinides have been tried with some success shortly after diagnosis." (PMID 39408828, 2024). "The P2-HNF4A promoter presents an important link between MODY-associated genes, as it harbors transcription factor binding sites for HNF-1A, HNF-1B, PDX1, and HNF-6." (PMID 38855865, 2024). "Regarding treatment, the percentage of patients with HNF1B-MODY treated with insulin was significantly higher than that of patients with HNF4A-MODY when compared with patients with T1DM (median 65.7% versus 36.4%, P = 0.00001 each)." (PMID 37016461, 2023). "Overall, this study contributes to the body of knowledge surrounding HNF1B-related MODY in the Croatian population." (PMID 37511676, 2023).
MODY (continued). "The diverse clinical manifestations observed in the study underline the importance of considering a broader range of features when diagnosing and managing patients with HNF1B-related MODY." (PMID 37511676, 2023). "In the meta-analysis including 61 eligible patients from 15 countries, hypomagnesemia was found in 92% of patients having HNF1B-related MODY." (PMID 37511676, 2023). "Of the seven total patients diagnosed with HNF1B-related MODY in this cohort, three of them had neuropsychiatric traits of the disease (one had dyslexia, one had autism, and one had paranoid schizophrenia)." (PMID 37511676, 2023). "The aim of this study was to investigate and gain a deeper understanding of HNF1B-related MODY within the Croatian population by analyzing the clinical characteristics and gene mutations present in affected patients." (PMID 37511676, 2023). "As our understanding of HNF1B-related MODY genetics continues to expand, the integration of genetic testing into clinical practice and personalized medicine will enhance the management of this complex disease." (PMID 37511676, 2023). "Extrapancreatic manifestations are rarely found in the different subtypes of MODY and HNF1B-related disease is an exception in this regard." (PMID 36672242, 2023). "It is interesting to note that, in this study of seven patients from Croatia diagnosed with HNF1B-related MODY, a wide range of clinical manifestations were observed." (PMID 37511676, 2023). "HNF1B-related MODY can be classified into two subtypes based on the type of genetic change that causes the condition: gene deletion and gene mutation." (PMID 37511676, 2023). "As seen in the seven described cases, personalized medicine through HNF1B-related MODY genetic testing holds great potential for improving patient care." (PMID 37511676, 2023). "This subtype of MODY is usually known as MODY5 or HNF1B/MODY, according to the most recent nomenclature." (PMID 36672242, 2023). "Seven patients were identified to have HNF1B-related MODY, which accounts for 5.9% of the total patients screened." (PMID 37511676, 2023). "As reported in literature, the rate of cardiovascular and microvascular complications among the patients with HNF1B-MODY is similar to that of patients with type 1 and type 2 diabetes." (PMID 36793123, 2023). "Patients with HNF1B–MODY have been shown to be effectively treated with sulfonylurea, repaglinide, GLP-1 RA, and insulin in case reports." (PMID 36573710, 2022). "Of the 11 missense variants in genes associated with MODY, the median PFI was 0.54 (Q1–Q3 0.44–0.81), with variants in HNF1B displaying the highest PFI of around 0.82." (PMID 36042188, 2022). "Mutations in fourteen different genes have been so far reported to cause several MODY subtypes (OMIM # 606391), the most common of which are due to mutations in GCK, HNF1A, HNF4A and HNF1B." (PMID 35052457, 2022). "LOF mutations in HNF1A, HNF1B and HNF4A, all leading to defective insulin secretion and reduced β-cells mass, cause some forms of MODY possibly associated with kidney and/or liver abnormalities." (PMID 35052457, 2022). "Extra-pancreatic symptoms have been reported in 40% of patients with HNF1B-MODY in the DPV database." (PMID 36294752, 2022). "HNF1B is also included in 24/26 MODY gene panels from NCBI gene registry highlighting the awareness of testing HNF1B in suspected MODY patients." (PMID 34789499, 2022). "Mutations in the hepatocyte nuclear factor 1-alpha (HNF1A), glucokinase (GCK), hepatocyte nuclear factor 4-alpha (HNF4A), and hepatocyte nuclear factor 1-beta (HNF1B) genes are the most frequently identified aetiologies of MODY." (PMID 34496959, 2021). "Pathogenic mutations in GCK, HNF1A, HNF1B, HNF4A, and PDX1 confirmed MODY in 7 families, giving an overall positivity rate of 22.6% in this cohort." (PMID 34373539, 2021). "Seven out of 31 index patients (22.6%) were confirmed as MODY with variants in genes encoding GCK, HNF1A, HNF1B, HNF4A, and PDX1." (PMID 34373539, 2021).